Y_RNA (Y RNA )
Gene: Miscellaneous RNA gene on chromosome 2 (137,715,332 to 137,715,440, forward strand). Ensembl gene ENSG00000222394.
Homologues: Orthologues: chimpanzee Y_RNA (100% identical), macaque Y_RNA (87% identical). Paralogues in human: Y_RNA (86% identical), RNY1 (85% identical), Y_RNA (85% identical), Y_RNA (84% identical), Y_RNA (83% identical), RNY1P11 (83% identical), Y_RNA (82% identical), RNY1P8 (81% identical), Y_RNA (81% identical), RNY1P10 (80% identical), RNY1P13 (80% identical), Y_RNA (80% identical), and 95 more.